EZH2 (enhancer of zeste 2 polycomb repressive complex 2 subunit)
Diseases named in the same sentence as EZH2 in open-access papers (continued):
Sharing a sentence is not in itself a finding about the gene and the disease.
cancer (continued). "MALAT1 was identified to interact with EZH2, the main methyltransferases of PRC2, and modulate downstream genes expression in multiple kinds of cancer cells." (PMID 39681821, 2024). "New classes of agents targeting androgen receptor signalling, poly (ADP-ribose) polymerase (PARP), enhancer of zeste homolog 2 (EZH2), cyclin-dependent kinases 4 and 6 (CDK4/6), and immunotherapies are being explored in cancer." (PMID 39131035, 2024). "As an EZH2 inhibitor, EPZ-6438 holds the potential to reverse cancer cell resistance to platinum-based chemotherapy drugs by modulating histone methylation levels and affecting related gene expression." (PMID 38525426, 2024). "Our findings elucidate that integrin α11 is upregulated by EZH2, forming a positive feedback circuit involving FAK-GLI-1 and contributing to drug resistance, cancer stem cell survival and EMT." (PMID 38664825, 2024). "Previous results have shown that CARM1 plays a role in modulating the antagonism between EZH2 and BAF155 to facilitate the H3K27me3 deposition by EZ in cancer cells." (PMID 38637528, 2024). "Many lncRNAs interacted with the histone-lysine N-methyltransferase EZH2 and DNA methyltransferases (DNMT) in both cancer-specific and pan-cancer patterns to methylate DNA downstream of target genes." (PMID 38248118, 2024). "It is well-accepted that EZH2 catalyze H3K27me3 through interacting with DNMT1, DNMT3a and DNMT3b in cancer cells." (PMID 38992588, 2024). "JARID2 binding sites are most significantly enriched in the promoters of the dysregulated genes in GBM but in the cancer cells, specifically, there is also enrichment of the catalytic subunit of PRC2: Enhancer of zeste homolog 2 (EZH2)." (PMID 38326875, 2024). "Several groups of epigenetic drugs, such as Enhancer of zeste homolog 2 (EZH2) inhibitors, HDAC inhibitors, and DNA methylation inhibitors, are playing an increasingly important role in the management of cancer." (PMID 39483548, 2024). "EZH2 was also shown to interact with DNMT1, DNMT3A, and DNMT3B in cancer cells and to result in the hypermethylation of genes, leading to increased permanent silencing of target genes." (PMID 39409007, 2024). "Because both EZH2 and ITGA11 genes supporting CSCs were overexpressed in the resistant cells, a cancer stem cell TF activation profiling array was conducted to identify regulatory transcription factors (TFs) responsible for the genes." (PMID 38664825, 2024). "Accordingly, GSK343 treatment, through EZH2 inhibition and H3K27 trimethylation reduction, demonstrated to significantly reduce the number of migrating cancer cells compared to those in the control group, in a concentration-dependent manner." (PMID 39204206, 2024). "Studies have previously demonstrated that the enhancer of zeste homolog 2 (EZH2) plays a regulatory role in Lipid Metabolism, and simultaneous targeting of EZH2 and Fatty Acid Synthesis results in cancer cell death." (PMID 39703843, 2024). "EZH2 is a target of SETD1A, which maintains cancer stem cell properties by triggering Wnt/β-catenin pathway activity." (PMID 39712244, 2024). "Utilizing the Cancer Cell Line Encyclopedia (CCLE) database, we found a positive correlation between EZH2 copy number and its expression levels in cells." (PMID 39518098, 2024). "The malignant feedback loop formed by the proteins EZH2 and HIF-1α often leads to unfavorable prognoses in a variety of cancers." (PMID 38911968, 2024). "The salient features of MALAT-1 include inducing EMT by activating many critical pathways in cancers, such as β-catenin, PI3K, Wnt, TGF-β, and Ezh2-Notch1." (PMID 38201661, 2024). "Specifically, it has been proven that knocking down EZH2 reduces OSCC cell proliferation and induces apoptosis, proving its involvement in cancer progression." (PMID 39204206, 2024). "Based on our observations, the genes involved in other cancer-related pathways, such as NFκB, VEGF, and mTOR, are all at least partially regulated by EZH2 in HCT116 cells in connection with TKS4." (PMID 38672463, 2024).
cancer (continued). "Enhancer of zeste homolog 2 (EZH2) is a pivotal epigenetic regulator, and its overexpression was detected in a wide range of cancers, including SCLC." (PMID 36345848, 2023). "Indeed, as EZH2 can promote cancer independently of its methyltransferase activity or by acting as a transcriptional coactivator, targeting EZH2 abundance may be more effective than enzymatic EZH2 inhibition against cancers that are driven by EZH2 methyltransferase-independent mechanisms." (PMID 36906655, 2023). "We found that the cells of early PCCs and corresponding PDOs expressed epithelial and cancer markers (AMACR, TMPRSS2-ERG, and EZH2)." (PMID 36769153, 2023). "In particular, SETD7, EZH2, G9a, SMYD2 and SUV4-20H2 have been extensively studied in cancer, and these proteins are being pursued as therapeutic targets of anticancer drugs." (PMID 38036730, 2023). "Enhancer of zeste homolog 2 (EZH2), known to modulate cancer development, is expressed strongly in the hippocampus." (PMID 36930428, 2023). "Meanwhile, considering the crucial role of EZH2 in cancer carcinogenesis and development through PRC2, numerous molecules have been synthesized and developed as potent EZH2 inhibitors, including DZNep, GSK126, tazemetostat, and CPI-169." (PMID 38264522, 2023). "Although several small compounds that compete with the EZH2 SAM binding site have entered clinical trials, they are mostly effective against a few cancer types because they are unable to completely stop the oncogenic activity of the PRC2 complex." (PMID 37667522, 2023). "EZH2 is also identified as a novel factor regulated by the HPV oncogenes protein E6 and E7 in cancer cervix cells." (PMID 37131568, 2023). "Enhancer of zeste homolog 2 (EZH2), the key catalytic subunit of polycomb repressive complex 2 (PRC2), is overexpressed and plays an oncogenic role in various cancers through catalysis-dependent or catalysis-independent pathways." (PMID 37210576, 2023). "In the present study, we determined that Roblitinib, a representative FGFR4 inhibitor, exerted anti-cancer effects in HCC cells, and these effects can be enhanced by EZH2 inhibitor CPI-169." (PMID 37085881, 2023). "This suggests a complex relationship of bidirectional influences between MHC I, APM, and EMT in cancer cells, with EMT regulators such as EZH2 having a dampening impact on the machinery." (PMID 38067396, 2023). "Tazemetostat acts by inhibiting enhancer of zeste homolog 2 (EZH2), preventing methylation of histone 3 at lysine 27 (H3K27), and abnormal methylation of this site is found in many cancers." (PMID 37631072, 2023). "EZH2 is responsible for methylation at H3K27 and has been shown to be over-represented in many cancer types including head and neck, prostate and breast cancers." (PMID 37168723, 2023). "There is an antagonistic relationship between EZH2 and SMARCB1 (as well as other subunits of the SWI/SNFc), resulting in genetic dependence on EZH2 in some SWI/SNF-mutant cancers." (PMID 37446319, 2023). "The cells from the prostate tissue, PCCs, and PDOs were assessed for the epithelial basal (CK5, p63) and luminal (CK18, AR1) markers, mesenchymal (vimentin) marker, and cancer (AMACR, TMPRSS2-ERG, and histone methyltransferase EZH2) markers by RT-PCR." (PMID 36769153, 2023). "There needs to be more research on how EZH2 inhibitors and ICB work together to treat ARID1A mutant cancer." (PMID 38008753, 2023). "Based on the intervention of noncancer-associated deaths, the correlation between the expression level of EZH2 and DSS in pan-cancer was examined using Cox regression analysis." (PMID 36545914, 2023). "The growth of EZH2 mutant DLBCL cell line Karpas422 and EZH2 WT rhabdoid cancer cell line was potently inhibited." (PMID 37667522, 2023). "First, we evaluated cancerous and normal prostate tissue samples for the presence of cancer markers AMACR and EZH2." (PMID 36769153, 2023).
cancer (continued). "This was the first study that had evaluated the effect of EZH2 on MPM TME composition, specifically on human monocytes and their impact on cancer cell responsiveness to tazemetostat." (PMID 36900330, 2023). "Although both HDAC inhibitors and EZH2 inhibitors, have FDA-approval in different cancers, these treatments are nonspecific and lead to a general decrease of silencing marks or increase of activating marks." (PMID 37670947, 2023). "The EZH2 GOF mutants, Y641F and A677G, showed a consistent set of transcriptional repressive targets that disturb several pathways in cancer, focal adhesion, and hematopoietic cell lineage." (PMID 37511137, 2023). "EZH2 is a S-adenosyl-L-methionine (SAM)-dependent methyltransferase, and its role as an epigenetic modulator in different types of cancer has been widely investigated." (PMID 36984801, 2023). "Spearman correlation analysis demonstrated a strong correlation between EZH2 expression and TMB, neoantigen, and MSI in multiple cancer types." (PMID 36545914, 2023). "We have previously reported the formation of a novel co-repressor complex driven by ERβ that involves NFκB and EZH2 in TNBC cells and have provided evidence that this complex plays an important role in mediating the anti-cancer effects of ERβ in TNBC." (PMID 36926316, 2023). "Enhancer of zeste homolog 2 (EZH2) is the catalytic subunit of PRC2 and is frequently overexpressed in various cancers, leading to tumorigenesis and poor prognosis." (PMID 37752998, 2023). "In both paired and unpaired samples of HCC patients, EZH2, G6PD, LGALS3 and PSMD14 were highly expressed in the cancer and lowly expressed in the paracancer, with statistically significant differences." (PMID 37853322, 2023). "By conducting a structure–activity relationship study that focused on exploring various linkers, we identified MS147, which preferentially degraded PRC1 components, BMI1 and RING1B, over PRC2 components: EED, EZH2, and SUZ12, in multiple cancer cell lines." (PMID 36737841, 2023). "EZH2, the enzymatic subunit of PRC2 that trimethylates histone H3 lysine 27 (H3K27me3) to promote transcriptional silencing, is aberrantly expressed in cancer." (PMID 37369946, 2023). "However, the multiomics features and immunological effects of EZH2 in pan-cancer remain unclear." (PMID 36545914, 2023). "EZH2 regulates self-renewal of different types of SCs through H3K27 trimethylation that represses the differentiation of normal and cancer SCs." (PMID 36769153, 2023). "Overexpressed EZH2 also participates in mediating EMT, one of the major factors contributing to cancer metastasis, besides conferring survival advantages." (PMID 38031139, 2023). "The expression of EZH2, an enzymatic subunit of polycomb repressive complex 2 (PRC2), is upregulated in various types of cancer cells, and also is under the influence of multiple oncogenic factors." (PMID 36759799, 2023). "The major function of EZH2 is to trimethylate H3K27 and repress gene expression, which has been mostly studied in dividing cells, such as stem cells and cancer cells." (PMID 37326884, 2023). "Enhancer of zeste-homolog 2 (EZH2), as an enzymatic subunit of PRC2, plays a cancer promoting role by catalyzing the methylation of histone H3 lysine 27 within PRC2 and regulating the G2/M transition of the cell cycle." (PMID 35864955, 2022). "The EZH2 inhibitor tazemetostat, the first FDA-approved HMT inhibitor for cancer treatment, is currently one of the most investigated compounds in the clinical trial, with its anti-cancer properties established in preclinical studies." (PMID 35438143, 2022). "The pan-cancer analysis results suggest that the eight hub genes (TXNRD1, TUBG1, SF3B4, PPM1G, PIGU, NDRG1, GRPEL2, and EZH2) were differentially expressed in gastrointestinal tumors." (PMID 36686830, 2022). "It is also reported that EZH2 and JARID2 regulate gene transcription by interacting with lncRNAs in ESCs and cancers." (PMID 36578923, 2022).
cancer (continued). "Since EZH2 is a core subunit of polycomb repressive complex 2 (PRC2), it plays an essential role in regulating cancer cell response to drugs." (PMID 36304988, 2022). "Enhancer of zeste homolog 2 (EZH2), a core component of polycomb repressive complex 2, plays an important role in cancer development." (PMID 35269532, 2022). "EZH2, the most important gene in the EGR signature, plays a dual role, often synergistically, in both cancer cells and the TME." (PMID 35911718, 2022). "EZH2 combines with EED, SUZ12, and RBBP4 to generate a PRC2 subunit, which is overexpressed in multiple types of cancer." (PMID 36686830, 2022). "Currently, several histone modification regulators, including DOT1L, DNMT1, EZH2, and KDM5B, have been reported to play a role in the TGFβ-stimulated ZEB2 transcriptional upregulation of many cancers." (PMID 35606881, 2022). "The lncRNA UFC1 repressed cancer cell apoptosis and promoted NSCLC progression, partially exerting oncogenic effects through the recruitment of EZH2 to epigenetically inhibit PTEN expression and activate downstream AKt signalling." (PMID 35379783, 2022). "Integrating analysis of the RNA and DNA binding profiles suggests EZH2 and JARID2 shift their binding ability from DNA to RNA in HepG2 cells to promote cancer development in HCC." (PMID 36578923, 2022). "For these 15 cancers, four prognosis-related indicators, including OS, DFS, PFI, and DSS, were used to evaluate the prognostic value of EZH2." (PMID 35627262, 2022). "In this regard, it has been reported that E2 regulates the activity of EZH2 through non-genomic signaling mediated by ERα and ERβ leads, which leads to phosphorylation of EZH2 by AKT and MAPK pathways in benign and cancer prostate cells." (PMID 35197928, 2022). "DOT1L, EZH2, and LSD1 inhibitors are currently being evaluated in clinical trials with evidence of therapeutic activity, underscoring their promise as anti-cancer agents." (PMID 35710782, 2022). "In HepG2 cells, we found EZH2 binds to the genes highly expressed in HCC patients, including those genes participating in the cancer pathway, indicating that EZH2 performs transcription activation roles in HCC by interacting with other proteins." (PMID 36578923, 2022). "EZH2 inhibitors reduces proliferation of BAP1-mutant mesothelioma cell lines, while platinum-based drugs and PARP-1 inhibitors should be able to target cancer cells with defective DNA repair mechanisms." (PMID 36318367, 2022). "Beyond EZH2, overexpression of another Polycomb protein in PRC1, chromobox homolog protein 2 (CBX2), is also associated with poor survival by maintaining CSCs, which might be an emerging approach targeting Polycomb proteins that could be used in cancer therapy." (PMID 35509102, 2022). "Overexpression, gain-of-function and loss-of-function mutations of the PRC2 catalytic subunit, the highly conserved Enhancer of zeste homolog 2 (EZH2) histone methyltransferase, are also frequently observed in many cancers." (PMID 35459932, 2022). "EZH2 interacts with several lncRs including PVT1 to modulate EMT and cancer stemness related to drug resistance." (PMID 36552560, 2022). "EZH2 (KMT6A) mediates the trimethylation of H3K27 (H3K27me3) and is overexpressed in many types of cancer, including prostate, kidney, breast and lung in which it promotes cell migration, colony formation and genomic instability." (PMID 36011043, 2022). "EZH2 is a part of PRC2, which plays an important role in the epigenetic regulation of gene expression, and regulates cancer cells proliferation, migration, invasion, and stemness and functions as an oncogenic factor in most solid tumors 15-17." (PMID 35813302, 2022). "Recently, a study reported that Ezh2 binds directly to Fbl, affects 2′-O-methylation in rRNA, and impacts the translation, of oncogenes through IRES through their 5′UTR in cancer cells." (PMID 35078993, 2022).
cancer (continued). "Furthermore, its important roles in cancer pathogenesis (initiation and progression) and maintenance of cancer hallmarks, including metastasis, aberrant signaling and metabolism, drug resistance, and immunity regulation, suggest that EZH2 targeting would highly impact the cancer cell biology." (PMID 36230683, 2022). "Therapeutic approaches targeting the role of BAP1 in cancer are currently under investigation, with on-going clinical studies assessing the effectiveness of PARP, EZH2 and HDAC inhibitors." (PMID 35381901, 2022). "It is worth noting that apart from EZH2, a variety of downstream effectors of NSD1 has been reported in different cancers." (PMID 36230787, 2022). "In this study, we used the small molecule inhibitors, UNC0642 (G9a inhibitor) and UNC1999 (EZH2 inhibitor) alone or in combination, to inhibit H3K9 and H3K27 methylation in different cancer cells." (PMID 35409271, 2022). "EZH2, a methyltransferase and core component of the PRC2 complex, has been reported to be highly expressed in diverse cancer types, including HCC." (PMID 35184652, 2022). "Both EZH2 and IDH1 are known epigenetic modifiers that contribute to the “stemness” of cancer through aberrant histone and DNA methylation, leading to the occurrence and progression of malignancies." (PMID 36292072, 2022). "This chemical also reduced HMT activity, EZH2 protein expression, and H3K27 trimethylation in histones extracted from cancer cells." (PMID 35327559, 2022). "The two-faced role of EZH2 in PFA and DMG—repressed but also essential in its residual activity—fits the overall highly ambiguous role of EZH2 in cancer." (PMID 34762160, 2022). "Due to the large number of cancers with overactive PRC2 signaling, current efforts are focused on developing small molecule inhibitors of EZH2 activity." (PMID 36066973, 2022). "EZH2 is the catalytic subunit of PRC2 and targeting EZH2 in cancer therapy has been considered an interesting option." (PMID 36553642, 2022). "In contrast, phosphorylated EZH2 methylates the transcription factor STAT3 at Lys180 (K180), which enhances STAT3-mediated transcriptional activation but also promotes cancer stem cell self-renewal and exerts oncogenic effects." (PMID 36076977, 2022). "Combining TAT peptides 1 and 2 markedly inhibited EZH2-mediated SMAD3 K53/K333 methylation, as well as cancer cell EMT." (PMID 35085106, 2022). "To investigate the role of EZH2 in GIST, we harvested cancer tissues and adjacent normal tissues from 46 GIST patients, and the results of RT-qPCR showed markedly increased EZH2 expression in GIST tissues." (PMID 35668081, 2022). "Our data showed that inhibition of EZH2 induces the expression of dsRNA and the transcription of a subset of ERVs in NSCLC cancer cells." (PMID 35912007, 2022). "Drugs such as the immunomodulatory drug lenalidomide or inhibitors of the epigenetic modulator EZH2 are promising leads, since they have been shown to restore CD58 expression in cancer cells." (PMID 35881486, 2022). "EZH2, the catalytic subunit of the polycomb repressor complex 2 (PRC2), promotes cancer development and progression through epigenetic silencing of tumor suppressors by trimethylation on histone H3 (H3K27me3)." (PMID 34356101, 2021). "Emerging data indicates that SWI/SNF alterations result in vulnerabilities in cancers, through directly targeting SWI/SNF complexes, targeting PRC2 via EZH2, or targeting downstream deregulation." (PMID 33481850, 2021). "Survival analyses using the TCGA PAM50-based dataset for human basal-like cancers showed that patients with low EZH2, high NFATC1 or low (EZH2/NFATC1)-ratio have a worse prognosis compared to EZH2 high, NFATC1 low or high (EZH2/NFATC1)-ratio patients." (PMID 34845197, 2021). "Enhancer of zeste homolog 2 inhibitors (EZH2i) have garnered increased attention owing to their anticancer activity by targeting EZH2, a well-known cancer-promoting factor." (PMID 33761979, 2021).